LCAT (lecithin-cholesterol acyltransferase)
Diseases named in the same sentence as LCAT in open-access papers (continued):
Sharing a sentence is not in itself a finding about the gene and the disease.
COVID-19 (6 papers, 2020 to 2025). A disease caused by infection with severe acute respiratory syndrome coronavirus 2. "The plasma concentrations of most apolipoproteins are markedly diminished in patients diagnosed with COVID-19, as well as lecithin cholesterol acyltransferase (LCAT) lipase, an enzyme indispensable for HDL maturation." (PMID 40090619, 2025). "Different PCAs were performed on the lipid profile, plasma concentrations of the 14 apolipoproteins and LCAT, and on the combination of these variables (lipid profile, apolipoproteome and LCAT concentration) of controls and COVID-19 patients." (PMID 36902035, 2023). "Plasma concentrations of Apo A-I, Apo A-II, Apo A-IV, Apo C-I, Apo C-II, Apo D, Apo H, Apo J, Apo M and LCAT were significantly reduced in COVID-19 patients, whereas the Apo E concentration was increased in these patients." (PMID 36902035, 2023). "Fourteen apolipoproteins and LCAT were measured by LC-MS/MS in plasma of 44 COVID-19 patients on admission to the ICU and 44 healthy control subjects." (PMID 36902035, 2023). "The heat map illustrates the correlations between apolipoproteins/LCAT and seven biological/clinical parameters in COVID-19 patients." (PMID 36902035, 2023). "Plasma apolipoproteins (Apo) A (I, II, IV), C(I, II), D, H, J and M and LCAT were lower in COVID-19 patients, whereas Apo E was higher." (PMID 36902035, 2023). "The concentrations of 10 apolipoproteins and LCAT were significantly modified in COVID-19 patients relative to controls." (PMID 36902035, 2023). "In addition, a decrease in the concentration of nine apolipoproteins and LCAT was found in COVID-19 patients, whereas only Apo E was increased relative to controls." (PMID 36902035, 2023). "Therefore, monitoring LCAT enzyme levels couldserve as an important marker for COVID-19 fatal outcomes." (PMID 40997940, 2025). "Furthermore, a decrease in LCAT activity and serum concentrations of this enzyme was observed in COVID-19 patients, which may explain the reduction in circulating HDL-C concentrations." (PMID 40090619, 2025). "In COVID-19 patients, LDL-cholesterol concentrations were correlated with Apo (a), Apo B100, Apo C-I, Apo E, Apo L1 and LCAT." (PMID 36902035, 2023). "Some HDL-raising pharmacological compounds have been considered as potential therapies for COVID-19, such as cholesteryl ester transfer protein (CETP)-inhibitors, recombinant cholesterol acyltransferase (LCAT)." (PMID 32892746, 2020). "Only Apo B100 and LCAT levels were significantly decreased in the non-survivors of COVID-19, while all other apolipoprotein levels were comparable between the two groups." (PMID 36902035, 2023). "Moreover, the plasma proteins HRG, FETUB, KNG1, LCAT, AHSG, and FN1 increase over time in abundance in the Munich cohort, thus suggesting their regulation during COVID-19 disease development." (PMID 34226277, 2021). "Low Apo B100 and LCAT levels may be predictive of non-survival in COVID-19 patients." (PMID 36902035, 2023).
nephrotic syndrome (6 papers, 2016 to 2022). A collection of symptoms that include severe edema, proteinuria, and hypoalbuminemia; it is indicative of renal dysfunction. "We presented a patient with nephrotic syndrome, which renal biopsy revealed classic features of LCAT deficiency." (PMID 28508023, 2016). "Moreover, a study on rats with nephrotic syndrome highlighted a reduction in plasma LCAT activity due to urinary excretion of the enzyme, leading to a condition of acquired LCAT deficiency." (PMID 33807271, 2021). "Moreover, deficiency of lecithin-cholesterol acyltransferase (LCAT), the enzyme that converts cholesterol to cholesteryl esters on the surface of HDL, which is caused by mutations in the LCAT gene, is responsible for some cases of nephrotic syndrome." (PMID 34442464, 2021).
colorectal cancer (5 papers, 2022 to 2024). A primary or metastatic malignant neoplasm that affects the colon or rectum. "LCAT has been extensively investigated as a potential biomarker for cancer, with studies indicating its association with invasive breast cancer as a common serum protein marker and its decreased activity in patients with colorectal cancer." (PMID 38654290, 2024).
Fabry disease (5 papers, 2014 to 2024). Fabry disease (FD) is a progressive, inherited, multisystemic lysosomal storage disease characterized by specific neurological, cutaneous, renal, cardiovascular, cochleo-vestibular and cerebrovascular manifestations. "Keratopathy is also present in inborn errors of metabolism, including mucopolysaccharidoses, mucolipidoses, cystinosis, tyrosinemia type II, Wilson disease, Fabry disease, Lecithin Cholesterol Acyltransferase Deficiency (LCAT)-related metabolic disease, and Tangier disease." (PMID 37239394, 2023).
hepatocellular carcinoma (5 papers, 2021 to 2025). A malignant tumor that arises from hepatocytes. "Since the protective gene LCAT has the lowest risk coefficient for hepatocellular carcinoma, we further explored the expression profile and identified the biological function of LCAT." (PMID 38195525, 2024). "This study identified a predictive signature comprising two specific hepatocyte genes, ADH4 and LCAT, which have been linked to the prognosis of hepatocellular carcinoma (HCC) and are considered protective factors." (PMID 38654290, 2024). "Previous studies have demonstrated that hypermethylation is associated with lower LCAT gene expression in hepatocellular carcinoma." (PMID 33805921, 2021). "Available data showed that mRNA levels of LCAT have been mostly explored within the prognostic models of hepatocellular carcinoma." (PMID 33805921, 2021). "And the expression is downregulated in hepatocellular carcinoma, suggesting that LCAT might involve in the processes of malignancy and prognostic." (PMID 36588724, 2022).
Cholestatic liver disease (4 papers, 2020 to 2023). "LpX is another abnormal lipoprotein particle that is usually undetectable in healthy individuals, but it can be found in patients with cholestatic liver disease or LCAT deficiency." (PMID 34572275, 2021). "LpX particles have been classically described in patients with cholestatic liver disease or LCAT deficiency." (PMID 34572275, 2021). "LpX is most frequently detected in patients with cholestatic liver disease as well as in those with lecithin:cholesterol acyltransferase (LCAT) deficiency, hepatic lipase (HL) deficiency, and after intravenous fat emulsion infusion." (PMID 33269016, 2020). "ApoA-I and apoA-II, major apolipoproteins that are carried by HDL, have been described to be decreased in cholestatic liver diseases together with impaired HL, lipoprotein lipase (LPL), and LCAT activities." (PMID 35268313, 2022).
Hyperglycemia (4 papers, 2020 to 2025). An increased concentration of glucose in the blood. "In contrast, hyperglycemia-induced glycation of apolipoprotein A1 inhibits its ability to activate lecithin-cholesterol acyltransferase, resulting in a 40% reduction in HDL cholesterol efflux efficiency in diabetic models." (PMID 40483478, 2025). "The LCAT activity in T1D is reported as increased according to hyperglycemia or unchanged and its role in atherogenesis is controversial." (PMID 36899434, 2023). "Taken together, these findings in tissue-specific cells show that hyperglycemia converges on major insulin, lipid, and fibrosis pathways by DNA methylation to regulate the expression of core genes that consist of but are unlikely to be limited to MTOR, RPTOR, IRS2, TXNRD1, LCAT, SMPD3, and COL1A2." (PMID 36633903, 2023).
Hypertension (4 papers, 2009 to 2024). The presence of chronic increased pressure in the systemic arterial system. "After further adjustments for LDL-cholesterol, HDL-cholesterol, the prevalence of hypertension, and albuminuria, the associations for LCAT activity with both all-cause mortality and ADHF remained significant." (PMID 39154733, 2024). "Increased prevalence of hypertension has been previously reported in LCAT mutation carriers." (PMID 24842300, 2014). "Hypertension was more prevalent in ABCA1 mutation carriers (p = 0.002) and LCAT mutation carriers (p = 0.02)." (PMID 24842300, 2014). "Interestingly, hypertension was more prevalent in both ABCA1 and LCAT mutation carriers, but seemed better regulated in ABCA1 mutation carriers." (PMID 24842300, 2014). "One possible explanation might be an increased activity of the lecithin:cholesterol acyltransferase (LCAT) in patients with hypertension." (PMID 19603071, 2009).
lipid metabolism disorders (4 papers, 2016 to 2025). "One of these patients was diagnosed with LCAT deficiency of the lipid metabolism disorders, and another patient was diagnosed with KSS of the mitochondrial diseases." (PMID 27086477, 2016).
lipoprotein glomerulopathy (4 papers, 2014 to 2024). "There was no clinicopathological data suggesting lipoprotein glomerulopathy or lecithin cholesterol acyltransferase deficiency, both of which are well-known causes of glomerular lipidosis." (PMID 37936128, 2023).
nonalcoholic fatty liver disease (4 papers, 2020 to 2025). "A higher nonalcoholic fatty liver disease activity score (NAS) indicated that LCAT KO hamsters had more severe steatohepatitis than WT hamsters did." (PMID 41195480, 2025). "Studies reported that LCAT participates in the process of nonalcoholic fatty liver disease and liver fibrosis." (PMID 36588724, 2022). "This is in contrast to elevated LCAT activity in subjects with non-alcoholic fatty liver disease (NAFLD), normal bilirubin levels and mildly elevated liver enzymes." (PMID 32927635, 2020).
renal dysfunction (4 papers, 2020 to 2025). "In this context, circulating LCAT levels predict CKD progression in individuals at early stages of renal dysfunction and in the general population." (PMID 33807271, 2021). "The present study shows that reduced plasma LCAT concentration predicts CKD progression over time in patients with renal dysfunction, and, even more striking, it predicts the impairment of kidney function in the general population." (PMID 32708515, 2020). "The main finding of our study is that the reduced plasma LCAT concentration predicts CKD progression over time in patients with renal dysfunction, and, even more striking, it predicts the impairment of kidney function in the general population." (PMID 32708515, 2020). "The results demonstrated that reduced circulating LCAT levels predict CKD progression in individuals at early stages of renal dysfunction independently of changes in HDL-c levels, confirming that changes in HDL subclass distribution contribute to the progression of renal damage." (PMID 33807271, 2021). "In this study, a higher ROS production in renal cells was observed in patients with lower serum LCAT concentration, and decreased plasma LCAT concentration was positively related to CKD development over time in patients with renal dysfunction." (PMID 40927188, 2025). "Other researchers have reported that taurine negatively affects lipid levels, reducing the efficacy of enzymes [lecithin cholesterol acyltransferase (LCAT), LPL] or serum factors [platelet-activating factor (PAF)] or GSH values, in an attempt to counterbalance renal dysfunction." (PMID 36699147, 2021). "Our data demonstrate that reduced circulating LCAT levels predict CKD progression at early stages of renal dysfunction independent of changes in HDL-c levels, supporting the hypothesis that changes in HDL subclass distribution, besides HDL-c levels contribute to the progression of renal damage." (PMID 32708515, 2020).
Alzheimer disease (3 papers, 2022 to 2026). A progressive, neurodegenerative disease characterized by loss of function and death of nerve cells in several areas of the brain leading to loss of cognitive function such as memory and language. "Limited studies have measured HDL CEC and, to a much lesser degree, LCAT activity in Alzheimer’s disease patients." (PMID 35884800, 2022). "It was reported that LCAT activity is reduced in cerebrospinal fluid of individuals suffering from Alzheimer’s Disease)." (PMID 36588724, 2022). "Moreover, we show that in Alzheimer's disease patients, CSF CEs are enriched in SFA, thus adding new insights into our recent observation that LCAT-mediated cholesterol esterification is hampered in Alzheimer's disease." (PMID 41936849, 2026). "In the current study, we determined whether HDL CEC and LCAT activity are altered in a large APOE genotyped cohort of elderly participants clinically diagnosed as either non-demented, MCI, or Alzheimer’s disease dementia (AD)." (PMID 35884800, 2022).
cardiac arrest (3 papers, 2021 to 2022). Cessation of breathing and/or cardiac function. "Since fish eye disease is characterized by an LCAT deficiency, it began an investigation into the effects of LCAT and cardiac arrest survival." (PMID 34250435, 2021). "Lecithin cholesterol-acyltransferase (LCAT) was found to be significantly changed, which was then combined with the term ‘cardiac arrest’ as input to a text-mining system for co-occurrence association." (PMID 35897884, 2022). "With that full picture of the ABC connection, the investigator quickly became excited and zeroed in on what became our discovery of LCAT as a druggable target for cardiac arrest." (PMID 34250435, 2021). "This, coupled with the association between several PUFAs and cardiac arrest found via plasma sample analysis and LBD further supported the potential of LCAT as a drug target for increasing cardiac arrest survival rates." (PMID 34250435, 2021). "The LBD results described here provided the spark of insight which began a line of inquiry into the relationship between LCAT and cardiac arrest." (PMID 34250435, 2021). "In this paper, we describe how we applied LBD techniques to discover lecithin cholesterol acyltransferase (LCAT) as a druggable target for cardiac arrest." (PMID 34250435, 2021). "LCAT regulates pathway A, and by decreasing LCAT availability we decrease PUFA flow into pathway A resulting in increased cardiac arrest survival." (PMID 34250435, 2021). "In this paper, we apply literature based discovery (LBD) to gain insights into the metabolic processes related to cardiac arrest and propose, and propose lecithin cholesterol acyltransferase (LCAT) as a druggable target for cardiac arrest." (PMID 34250435, 2021). "The coupled metabolic and disease LBD findings provided the spark of insight which began a line of inquiry into the connection between LCAT and cardiac arrest via its effect on PUFA availability." (PMID 34250435, 2021). "This led to identification of LCAT as a promising drug target for cardiac arrest." (PMID 35897884, 2022). "Very little literary evidence was found for a direct relationship between LCAT and cardiac arrest and the mechanisms as to how it may be related were unknown." (PMID 34250435, 2021). "In the investigation, we found that decreased LCAT activity may increase cardiac arrest survival rates by increasing ω-3 polyunsaturated fatty acid availability in circulation." (PMID 34250435, 2021). "Furthermore, the KD system also provided a mechanistic route of LCAT with respect to cardiac arrest, i.e., decreased LCAT activity may increase ω-3 polyunsaturated fatty acid availability in circulation, affecting cardiac arrest survival rates." (PMID 35897884, 2022). "In it, we stated that there is a potentially interesting, yet unexplored link between fish eye disease (also called partial lecithin cholesterol acyltransferase (LCAT) deficiency) and cardiac arrest, but excluded details and lacked any empirical evidence to support this hypothesis." (PMID 34250435, 2021). "Furthermore, no studied established the link between LCAT, ω-3 PUFA, and cardiac arrest." (PMID 34250435, 2021).
cholestasis (3 papers, 2021 to 2024). Impairment of the bile flow caused by obstruction within the liver, or outside the liver in the bile duct system. "This abnormal lipoprotein usually occurs in LCAT deficiency and severe cholestasis." (PMID 34692787, 2021).
dyslipidaemia (3 papers, 2020 to 2022). "SNPs in LCAT may independently contribute to dyslipidaemia among Ghanaian HIV-infected individuals on HAART, thus, allowing genetic and/or functional differential diagnosis of dyslipidaemia and creating an opportunity for potentially preventive options." (PMID 33173066, 2020). "Yet, dyslipidaemia may not independently occur as it may be worsened by single nucleotide polymorphisms (SNPs) in lecithin cholesterol acyltransferase (LCAT) and lipoprotein lipase (LPL)." (PMID 33173066, 2020). "The study has demonstrated the existence of SNPs in LCAT and LPL among HIV-infected individuals with dyslipidaemia in Ghana." (PMID 33173066, 2020).
liver fibrosis (3 papers, 2022 to 2025). "Exogenous supplementation with LCAT also relieve liver fibrosis and increase BMD in the mouse HOD model by promoting the reversal of cholesterol transport from the bone to the liver via liver-bone axis." (PMID 36588724, 2022). "The fibrosis area was negatively correlated with LCAT which suggesting that LCAT could be exploited as a specific biomarker for detecting liver fibrosis." (PMID 36588724, 2022). "For instance, liver fibrosis is associated with increased levels of TGF-β1, and various inflammatory cytokines, as well as decreased production of insulin-like growth factor, lecithin-cholesterol acyltransferase, and alterations in vitamin D and parathyroid hormone metabolism." (PMID 39503877, 2025). "Thus, these discoveries open the possibility that recombinant LCAT may be a treatment for both HOD and liver fibrosis." (PMID 36588724, 2022).
myocardial infarction (3 papers, 2021 to 2024). Gross necrosis of the myocardium, as a result of interruption of the blood supply to the area, as in coronary thrombosis. "The marked decrease in LCAT concentrations observed in myocardial infarction patients may have a causal relationship with its aetiology in these patients." (PMID 39114750, 2024). "Myocardial infarction patients had the lowest mean plasma LCAT level." (PMID 39114750, 2024). "A similar trend was observed in the non-conventional lipid-related ASCVD biomarkers (PON-1 and LCAT), where myocardial infarction and IHD patients were noted to have the lowest concentrations of plasma PON-1 and LCAT." (PMID 39114750, 2024). "It is noteworthy that the mean plasma LCAT concentrations of the different subclasses of ASCVD showed significant variations among different groups, with the lowest value observed in myocardial infarction patients." (PMID 39114750, 2024). "The present study demonstrated significant decreases in plasma PON-1 and LCAT levels with severe alterations in atherogenic lipids and lipoproteins in ASCVD patients, especially the subtypes of myocardial infarction and IHD." (PMID 39114750, 2024). "A specific analysis of the HDL3 subfraction in that study revealed a coordinated decrease in the content of Apo L1 and lecithin:cholesterol acyltransferase (LCAT), a key enzyme in HDL metabolism, in HeFH patients with a fatal myocardial infarction during follow-up." (PMID 34356876, 2021).
Nephropathy (3 papers, 2016 to 2023). A nonspecific term referring to disease or damage of the kidneys. "Thus, LCAT protein, which has been inversely associated with the progression of nephropathy, was similarly decreased in both Nx groups." (PMID 36829843, 2023).